RAB9A (RAB9A, member RAS oncogene family)
Diseases named in the same sentence as RAB9A in open-access papers:
RAB9A is named in the same sentence as 41 diseases in open-access papers, as found by Europe PMC text mining. Sharing a sentence is not in itself a finding about the gene and the disease. The quoted sentences say what the papers report.
melanoma (8 papers, 2019 to 2025). A malignant, usually aggressive tumor composed of atypical, neoplastic melanocytes. "The underlying mechanism of ISL with circ_0002860/miR-431-5p/RAB9A was unraveled in melanoma." (PMID 37020694, 2023). "In conclusion, ISL inhibited cell progression (proliferation, cell cycle progression, migration, invasion and EMT) and promoted apoptosis of melanoma via mediating the circ_0002860/miR-431-5p/RAB9A axis." (PMID 37020694, 2023). "Through the detection of RT-qPCR and western blot, RAB9A was found to be upregulated in melanoma tissues and cells." (PMID 37020694, 2023). "The current data suggested that circ_0002860 was a miRNA sponge of miR-431-5p and the downstream target RAB9A was regulated by circ_0002860 through mediating miR-431-5p in melanoma cells." (PMID 37020694, 2023). "Member RAS oncogene family (RAB9A) exerted the oncogenic function in tumorigenicity and development of melanoma." (PMID 37020694, 2023). "The current data indicates that ISL suppressed cell malignant progression of melanoma via targeting the circ_0002860/miR-431-5p/RAB9A pathway." (PMID 37020694, 2023). "The miR-431-5p/RAB9A axis was partly responsible for the antitumor response of ISL in melanoma cells." (PMID 37020694, 2023). "The levels of circ_0013359, microRNA-136-5p (miR-136-5p), and member RAS oncogene family (RAB9A) in melanoma tissues and cells were detected using quantitative reverse transcriptase-polymerase chain reaction or western blot." (PMID 34056112, 2021). "RAB9A is a subtype of RAB9, which plays a significant role in the biological process of breast cancer cells; silencing of RAB9 can attenuate the malignant phenotypes of melanoma cells." (PMID 33968929, 2021). "Circ_0013359 and RAB9A levels were increased, while the miR-136-5p level was reduced in melanoma tissues and cells." (PMID 34056112, 2021). "Compared with normal tissues, RAB9A mRNA and protein levels were significantly increased in melanoma tissues." (PMID 34056112, 2021). "Additionally, the knockdown of RAB9A diminishes the proliferation and invasion of melanoma cells, while also fostering apoptosis." (PMID 40141028, 2025). "In melanoma, miR-150-5p negatively regulates the oncoprotein RAB9A." (PMID 37921969, 2024). "Furthermore, cell assays manifested that ISL inhibited the melanoma progression via regulating the circ_0002860/miR-431-5p axis and miR-431-5p/RAB9A axis." (PMID 37020694, 2023). "Whether circ_0002860 can induce the sponge effect to regulate RAB9A remains unknown in melanoma cells." (PMID 37020694, 2023). "The function of ISL was related to miR-431-5p/RAB9A axis in melanoma progression." (PMID 37020694, 2023). "Depletion of circ_0013359 hindered melanoma progression by regulating miR-136-5p/RAB9A axis." (PMID 34056112, 2021). "In this report, we clarified that miR-136-5p blocked melanoma cell development via targeting RAB9A." (PMID 34056112, 2021). "In the meantime, we explored the interaction between circ_0013359 and miR-136-5p/member RAS oncogene family (RAB9A) axis in melanoma, which may provide new therapeutic targets for melanoma." (PMID 34056112, 2021). "A previous study reports that RAB9A functions as an oncogene in melanoma and breast cancer cells." (PMID 32420351, 2020). "Our findings are consistent with the role of RAB9A in melanoma and breast cancer cells." (PMID 32420351, 2020). "In addition, RAB9A knockdown can inhibit the proliferation, migration, and invasion of melanoma cells and induce apoptosis." (PMID 32420351, 2020). "In addition, miR-136-5p suppressed melanoma progression by targeting RAB9A." (PMID 34056112, 2021). "Furthermore, circ_0013359 contributed to melanoma progression via modulating miR-136-5p/RAB9A axis, suggesting that circ_0013359 might be a promising biomarker for melanoma treatment." (PMID 34056112, 2021).
breast carcinoma (4 papers, 2020 to 2024). "RAB9A is known to be highly detected in breast cancer samples and is tightly linked to the biological progression of breast cancer." (PMID 33968929, 2021).
hepatocellular carcinoma (2 papers, 2023 to 2024). A malignant tumor that arises from hepatocytes. "In the circular RNA form, LNPEP was reported to enhance Ras-related protein Rab-9A expression levels by sponging miR-532–3p under hypoxia and promoting invasiveness in hepatocellular carcinoma cells." (PMID 36900344, 2023).
malaria (2 papers, 2012 to 2018). Malaria is a serious and sometimes fatal disease caused by a parasite that commonly infects a certain type of mosquito which feeds on humans. "In conclusion, our results show that the increase in phagocytosis of malaria parasites or E. coli, observed after Rab14 or Rab9a silencing, respectively, is due to an increase in the surface expression of the phagocytic receptors involved in the process." (PMID 30158654, 2018). "We have previously shown that Rab14 or Rab9a silencing leads to an increase in the phagocytosis of malaria parasites or E. coli, respectively." (PMID 30158654, 2018). "Here, we investigated the mechanism by which the malaria parasite Plasmodium berghei and the bacterium Escherichia coli subvert phagocytosis through the modulation of Rab14 or Rab9a expression, respectively." (PMID 30158654, 2018).
measles (2 papers, 2009 to 2011). A highly contagious viral infection caused by the measles virus. "It has also been found that Rab9 GTPases are a key component for the replication of several viruses, including HIV1, Ebola, Marburg, and measles making Rab9 a potential target for inhibiting replication of some viruses." (PMID 19442299, 2009).
Niemann-Pick disease type C (2 papers, 2016 to 2022). NPC is a complex lipid storage disease mainly characterized by the accumulation of unesterified cholesterol in the late endosomal/lysosomal compartment. "Specifically DRABAL suggests the Thiabendazole drug as a common activator of the NCP1 and Rab-9A proteins, both of which are designed to identify treatment modalities for the Niemann–Pick type C disease." (PMID 27895719, 2016).
invasive breast carcinoma (1 paper, 2020). A carcinoma that infiltrates the breast parenchyma. "As shown in, PPBP and RAB9A, show a significant change in gene expression in DCIS but no change in gene expression in invasive breast cancer tissue from human clinical samples." (PMID 32051475, 2020). "Therefore, RAB9A hypermethylation and potential downregulation could be a contributing factor to maintaining the DCIS stage without progression to invasive breast cancer." (PMID 32051475, 2020).
leukemia (1 paper, 2016). A malignant (clonal) hematologic disorder, involving hematopoietic stem cells and characterized by the presence of primitive or atypical myeloid or lymphoid cells in the bone marrow and the blood. "Selective induction of mitophagy was associated with the upregulation and localization of RAB9A on the mitochondrial membrane in both wild-type and Atg7−/− leukemia cells." (PMID 27091640, 2016). "As the upregulation of the alternative autophagy-essential protein RAB9A was associated with Atg7 deletion in K562 cells, we silenced Rab9A with RNA interference to analyze the importance of the RAB9A protein in alternative mitophagy in leukemia cells." (PMID 27091640, 2016). "When the leukemia cells were treated with the alternative autophagy inhibitor brefeldin A or when the RAB9A was knocked down, this mitophagy was prohibited." (PMID 27091640, 2016). "Indeed, enhanced alternative autophagy was stimulated by 20 μM etoposide, as demonstrated by a further pronounced increase in RAB9A and BECN1 in K562 leukemia cells." (PMID 27091640, 2016).
liver cancer (1 paper, 2020). An epithelial or non-epithelial malignant neoplasm that arises from the liver. "In order to investigate the biological function of RAB9A in human liver cancer, loss- and gain-of-function assays were performed." (PMID 32420351, 2020). "In order to investigate the action mechanism underlying the procancer effect of RAB9A in human liver cancer cells, we proposed that the AKT/mTOR signaling pathway might be associated with the biological function of RAB9A." (PMID 32420351, 2020). "We found that RAB9A significantly promoted the proliferation, colony formation, invasion, and migration of human liver cancer cells." (PMID 32420351, 2020). "To identify the function of RAB9A in liver cancer, we used plasmid to upregulate RAB9A in Hep3b cells and used shRNA to downregulate RAB9A in HepG2 cells." (PMID 32420351, 2020). "Based on these results, RAB9A also plays an important oncogenic role in the progression of liver cancer." (PMID 32420351, 2020). "In our study, we first observed that RAB9A acted as an oncogene in the progression of human liver cancer." (PMID 32420351, 2020). "In this study, we found that RAB9A activated the AKT/mTOR signaling pathway in human liver cancer cells." (PMID 32420351, 2020). "We continued to investigate whether RAB9A could affect the cell invasion and migration of human liver cancer cells." (PMID 32420351, 2020). "In this study, we identify that RAB9A promotes the tumor aggressive progression of human liver cancer in vitro, which may be mediated by blocking AKT signaling pathways." (PMID 32420351, 2020). "Therefore, identifying proteins that interact with RAB9A in liver cancer cells is one of our future research directions and will provide new targets for the treatment of liver cancer." (PMID 32420351, 2020). "In addition, little is known about the specific molecular mechanisms by which RAB9A functions in liver cancer cells." (PMID 32420351, 2020). "Finally, we found that RAB9A plays a procancer role in liver cancer cells by affecting the activation of the AKT/mTOR signaling pathway." (PMID 32420351, 2020). "Our study provides a novel perspective on the potential role of RAB9A in liver cancer therapy." (PMID 32420351, 2020). "Our data suggest that RAB9A plays a carcinogenic role in human liver cancer progression partially through AKT signaling pathways, suggesting that RAB9A may serve as a potential therapeutic target for liver cancer therapy." (PMID 32420351, 2020). "Therefore, we cannot determine that the role of RAB9A in liver cancer cells is GTP-dependent or GTP-independent." (PMID 32420351, 2020). "Importantly, RAB9A activated the AKT/mTOR signaling pathway in human liver cancer cells." (PMID 32420351, 2020). "However, the role of RAB9A in tumors, including liver cancer, is still unknown." (PMID 32420351, 2020). "However, the role of RAB9A in other tumors, including liver cancer, is still unknown." (PMID 32420351, 2020).
Miscarriage (1 paper, 2015). A pregnancy that ends at a stage in which the fetus is incapable of surviving on its own, defined as the spontaneous loss of a fetus before the 22th week of pregnancy. "The remaining genes assayed had either very low or no expression in cultured chorionic villi from controls (PARK, LIPC, CTNNA3, EGFL6, GPM6B, RAB9A, POU6F2 and C7orf10) and were not assessed in miscarriages." (PMID 25674159, 2015).
pancreatic adenocarcinoma (1 paper, 2022). "As additional control, we analyzed secretion of transfected His6/myc-tagged PAUF (pancreatic adenocarcinoma up-regulated factor), a cargo of CARTS (carriers of the TGN to the cell surface) that bypass membranes related to Vps26 or Rab9a function." (PMID 35314489, 2022).
infection (14 papers, 2012 to 2024). The state of being infected such as from the introduction of a foreign agent such as serum, vaccine, antigenic substance or organism. "In this study, we show that Rab9a supports HPV type 16 (HPV16) entry by associating with incoming HPV early during infection and modulating the association of retromer and HPV." (PMID 37703297, 2023). "In contrast, the GTP- and GDP-bound forms of Rab9a have opposing effects on HPV infection, with excess GDP-Rab9a supporting infection and excess GTP-Rab9a inhibiting it." (PMID 37703297, 2023). "Although Rab9a is required for efficient infection by HPV pseudovirus (PsV), its role in this process has not been investigated." (PMID 37703297, 2023). "Forty-eight hpi we used flow cytometry to quantify GFP fluorescence as a measure of infection and anti-HA staining to document successful expression of the mutant Rab9a protein." (PMID 37703297, 2023). "Rab9a is in proximity to HPV as early as 3.5 h post-infection, prior to the Rab7-HPV interaction, and HPV displays increased association with retromer in Rab9a knockdown cells, even in the presence of dominant negative Rab7." (PMID 37703297, 2023). "Similar results were obtained with E. coli and Rab9a, i.e. infection with E. coli increases the expression of Rab9a and Rab9a overexpression impairs the phagocytosis of E. coli, whereas Rab9a silencing has the opposite effect." (PMID 30158654, 2018). "To assess the effect of the Rab family on RSV replication, we depleted Rab1a, Rab2a, Rab4a, Rab5a, Rab6a, Rab7a, Rab8a, Rab9a, and Rab11a by treating A549 cells with specific siRNAs (or control siRNA) for 24 h, followed by infection with purified RSV A2 and incubation for another 36 h." (PMID 33504607, 2021). "Then we use Brucella wild type (WT) infection the cells after the silencing of Rab9A and RAP1B." (PMID 33489935, 2020). "This is suggested by the observation that Rab14 and Rab9a, whose expression is upregulated upon infection with P. berghei and E. coli or S. enterica, respectively, are negative regulators of the phagocytosis of these microorganisms, since their silencing leads to an increase in phagocytosis." (PMID 22911692, 2012). "We also attempted to analyze the protein levels of Rab9a and Rab14 upon infection." (PMID 22911692, 2012). "Similarly, observed downregulation Rab9a GEF-encoding genes, DENND2a and DENND2b, in the E phase of infection does not correlate with the increase of Rab9a membrane-associated pool within the inner PrAC." (PMID 33042998, 2020). "To determine whether HPV and Rab9a are in proximity during HPV entry, we next conducted L1-Rab9a PLA at various times after infection." (PMID 37703297, 2023).
tumor (9 papers, 2013 to 2025). "miR-411-5p inhibition or RAB9A overexpression reversed the anti-tumor effects caused by circSIPA1L1 knockdown." (PMID 33968929, 2021). "In this context, we assessed the clinical value of 8 genes (RAB2B, RAB3B, RAB9A, RAB11B, RAB27A, RAB27B, STX1A, and VAMP7), which are implicated in sEVs biogenesis, as well as their association with overall and tumor-derived plasma sEVs levels." (PMID 36980570, 2023). "Taken together, tumor growth was suppressed by ISL via mediating the circ_0002860/miR-431-5p/RAB9A axis." (PMID 37020694, 2023). "Moreover, Rab9a downregulation reversed the tumor-suppressive effect of Tmbim1, indicating that Rab9a is essential for TMBIM1-mediated suppression of tumor progression through the proposed mechanism." (PMID 41197720, 2025). "We observed that Rab9a knockdown alone significantly promoted tumor growth." (PMID 41197720, 2025). "Overall, Rab9A affected tumour progression through the AKT/mTOR pathway." (PMID 40293576, 2025). "Finally, we knocked down Rab9a in mice using adenoviral transduction and then orthotopically implanted tumor cells into the liver." (PMID 41197720, 2025). "Meanwhile, animal assay validated that circ_0002860 could mitigate the ISL-induced tumor growth suppression by the regulation of miR-431-5p and RAB9A levels." (PMID 37020694, 2023). "Hence, ISL was considered to act as a tumor repressor by targeting circ_0002860 to modulate miR-431-5p/RAB9A axis." (PMID 37020694, 2023). "Mechanistically, circSIPA1L1 could serve as a miR-411-5p molecular sponge to increase RAB9A expression, which was confirmed to be a tumor promoter mediating carcinogenesis." (PMID 33968929, 2021). "Tumor growth was reduced by ISL in vivo through downregulating circ_0002860 to regulate miR-431-5p and RAB9A levels." (PMID 37020694, 2023). "In addition, high tumor expression of RAB27A, RAB27B, RAB9A, RAB11B, and STX1A was favorable of a 5-year survival (p = 0.038, p = 0.015, p = 0.008, p = 0.002, and p = 0.028, respectively)." (PMID 36980570, 2023). "Importantly, in addition to the aberrant reactivation of genes on the inactive X, aberrant silencing of several genes that normally escape XCI, such as RAB9A, BCOR, RPL39, or PNPLA4 was also observed in tumor cell lines." (PMID 25653311, 2015).
cancer (6 papers, 2018 to 2025). A tumor composed of atypical neoplastic, often pleomorphic cells that invade other tissues. "It has been reported that the downstream genes of ZAFS1/miR-150 includes VEGFA, ST6GAL1, ZEB1 and RAB9A in cancer cells [16,]." (PMID 39296014, 2024). "Among potential GSDMB interacting cancer and autophagy proteins, some Rab GTPases were found (Rab5C, Rab7A, Rab9A and Rab15)." (PMID 36163066, 2022). "Moreover, inhibition of PINK1/parkin- or ras-related protein Rab-9A (Rab9a)-mediated mitophagy has been shown to radiosensitize cancer cells." (PMID 40943612, 2025).
bacterial infection (1 paper, 2012). "Further studies should be performed in order to dissect the mechanism by which Rab9a plays a role in bacterial infection, through the modulation of phagocytosis." (PMID 22911692, 2012). "The observation that the upregulation of Rab9a inhibits phagocytosis by macrophages suggests that this upregulation, which is induced by bacterial infection, could serve as an immune evasion strategy." (PMID 22911692, 2012).
RAB9A also shares sentences with these, for which no sentence is quoted: ischemia (3 papers); cognitive deficits (2); Alzheimer disease (1); asthma (1); brain tumor (1); cardiac hypertrophy (1); cardiomyopathy (1); cervical cancer (1); chronic myelogenous leukemia (1); diabetic cardiomyopathy (1); Ebola (1); heart disease (1); hepatitis B virus infection (1); Hypokalemia (1); immune deficiency (1); lung carcinoma (1); lymphoma (1); lysosomal storage disease (1); myocardial ischemia (1); neuroblastoma (1); Obesity (1); opioid use disorder (1); osteosarcoma (1); ovarian carcinoma (1); Salmonella Infections (1); viral infection (1).